EGFR (epidermal growth factor receptor)
Diseases named in the same sentence as EGFR in open-access papers (continued):
Sharing a sentence is not in itself a finding about the gene and the disease.
gallbladder cancer (continued). "A case of stage IV gallbladder cancer with no EGFR mutation having long complete response to treatment with EGFR-TKI plus chemotherapy has been reported." (PMID 32622356, 2020). "To determine the significance of EGFR and ERBB2 constitutive phosphorylation and KRAS mutant alleles in gallbladder cancer cells, we set out to establish whether expression of ERBB2 is required for gallbladder tumor cell survival." (PMID 30304546, 2019). "The patient with gallbladder cancer presented in this report had a rarely encountered compete response in the absence of a tumor associated EGFR mutation." (PMID 20961434, 2010). "suggests that KRAS G12V but not KRAS G13D mutations may prevent gallbladder cancer patients from responding to anti-EGFR therapy, KRAS G13D mutation as sensitive but G12V as resistant to anti-EGFR therapy." (PMID 40231011, 2024). "Since simple cholecystectomy is regarded as feasible and safe in the early stage of gallbladder cancer, more appropriate selection criteria of simple cholecystectomy could be established and major surgery can be avoided, based on the present EGFR-targeted florescent imaging." (PMID 35701793, 2022). "EGFR may be a crucial target in the conversion of gallstones to gallbladder carcinoma." (PMID 30719056, 2019). "It has been demonstrated that PLEK2 interacts with epidermal growth factor receptor (EGFR) and suppresses EGFR ubiquitination mediated by c-CBL, leading to downstream CCL2 transcriptional overexpression and EMT process activation in gallbladder cancer." (PMID 34869363, 2021). "Alterations of epidermal growth factor receptor (ERBB) family have been reported in CCA, mostly in gallbladder cancer (19%) and in pCCA/dCCA (17%), as compared to iCCA (4.8%)." (PMID 32168869, 2020). "In gallbladder carcinoma GBC-SD cells, lupeol was shown to induce apoptosis and inhibit invasion by downregulating the activity of p-EGFR and MMP-9." (PMID 32571387, 2020). "Consistent with whole exome findings, we observed varying levels of EGFR and ERBB2 constitutive phosphorylation in all gallbladder cancer cell lines based on their phospho‐proteome and follow up validation by western blot analysis." (PMID 30304546, 2019). "Aside from cytotoxic chemotherapeutic agents, several targeted agents against EGFR, VEGF or MEK have also been reported to be useful in treating gallbladder cancer." (PMID 30016995, 2018). "ECC EGFR amplified patients had improved OS, whereas the amplification significantly correlated with poor PFS (p = 0.03) in gallbladder carcinoma patients." (PMID 29352306, 2018). "It was also shown that targeting EGFR/HER2 pathways enhances the antiproliferative effect of gemcitabine in biliary tract and gallbladder carcinomas." (PMID 28412732, 2017). "Next, we examined the expression levels of gallbladder cancer-related markers (ERBB2, CA19-9, CEA, EGFR, Ki67, PD-L1) using immunohistochemistry; all markers were detected in the PDX, PDO, and PT samples with the exception of PD-L1, which is a negative prognosticator for gallbladder cancer." (PMID 36591461, 2022). "The other one is EGFR, which is involved in the EMT process activation in gallbladder cancer." (PMID 34869363, 2021). "Additionally, the gallbladder is a good candidate for fluorescent imaging using EGFR-targeted antibodies, since EGFR is overexpressed in gallbladder cancer regardless of the cancer stage." (PMID 35701793, 2022).
gallbladder cancer (continued). "Our in vitro test confirmed that NOZ (gallbladder cancer cell line) and other bile duct cancer cell lines, such as SNU308 (gallbladder cancer), SNU478 (ampulla of vater cancer), and SNU1196 (hilar cancer), also expressed EGFR (data not shown)." (PMID 35701793, 2022).
non-squamous non-small cell lung cancer (47 papers, 2011 to 2026). "Activating mutations in the epidermal growth factor receptor (EGFR) gene is a relatively frequent event in patients with advanced non-squamous non-small-cell lung cancer (NSCLC), occurring in 15 to 50% of cases." (PMID 41590374, 2026). "Several head-to-head meta-analyses have compared the efficacy and safety of different first-line treatments in patients with EGFR mutation-positive (M+) advanced or metastatic non-squamous non-small cell lung cancer (nsq-NSCLC)." (PMID 39882445, 2024). "Testing for epidermal growth factor receptor (EGFR) mutations is an essential recommendation in guidelines for metastatic non-squamous non-small-cell lung cancer, and is considered mandatory in European countries." (PMID 37713929, 2023). "Approximately, 12–15% of non-squamous non-small cell lung cancers (NSCLC) are molecularly characterized by an activating mutation in the epidermal growth factor receptor (EGFR)." (PMID 37198447, 2023). "Incidence rates of non-squamous non-small cell lung cancer by EGFR mutation status, showing the estimates based on the EGFR mutation tested proportions." (PMID 33961689, 2021). "The ORR and DCR of the first and second generation TKI for EGFR mutation positive non-squamous non-small cell lung cancer (NSq-NSCLC) were about 56.0%-71.2% and 90.0%-91.7%, respectively." (PMID 33869057, 2021). "Incidence rates of non-squamous non-small cell lung cancer by EGFR mutation status, showing the estimates for 100% testing." (PMID 33961689, 2021). "Non-squamous non-small cell lung cancer (NSCLC) patients with Epidermal Growth Factor Receptor (EGFR) mutation benefit from targeted treatments." (PMID 33961689, 2021). "Epidermal growth factor receptor (EGFR) mutations are observed in approximately 10-15% of the Caucasian population 1 and more than 50% of the Asian population 2 with non-squamous non-small cell lung cancer (NSCLC)." (PMID 32127933, 2020). "Epidermal Growth Factor Receptor (EGFR) gene mutation testing is a critical first step in the personalised treatment of patients with non-squamous non-small cell lung cancer (NSCLC)." (PMID 29254176, 2017). "The presence of epidermal growth factor receptor (EGFR) mutations is predictive of a better response to EGFR tyrosine kinase inhibitors (EGFR-TKIs) and initial chemotherapy in advanced non-squamous non-small cell lung cancer (NSCLC)." (PMID 21924037, 2011). "Epidermal growth factor receptor (EGFR) mutations are described in 10–15% of Caucasian patients and in 50% of Asian patients with non-squamous non-small cell lung cancer (NSCLC)." (PMID 40361442, 2025). "In 2015, guidelines recommended the evaluation of only two molecular markers: epidermal growth factor receptor (EGFR) mutations and anaplastic lymphoma kinase (ALK) fusions, in patients with non-squamous non-small cell lung cancer." (PMID 39064008, 2024). "Osimertinib is regarded as a promising third-generation epidermal growth factor receptor (EGFR) tyrosine kinase inhibitor (TKI) for advanced non-squamous non-small cell lung cancer (NSCLC) patients who developed T790M." (PMID 38500118, 2024). "A phase I study NCT03050411 aims to evaluate the dosage and efficacy of apatinib, a TKI that selectively inhibits VEGFR-2, when given in combination with EGFR-TKI in the treatment of EGFR-TKI-resistant advanced non-squamous non-small cell lung cancer." (PMID 36910653, 2023). "Telisotuzumab vedotin is a MET-targeting antibody-drug conjugate that has demonstrated a good treatment response in patients with EGFR wild-type MET-overexpressing non-squamous non-small cell lung cancer." (PMID 36033470, 2022). "Another signaling pathway of EGFR tyrosine kinase inhibitor have been effectively used as a promising target for clinical treatment of non-squamous non-small cell lung cancer." (PMID 33430939, 2021).
non-squamous non-small cell lung cancer (continued). "In about 15 to 50% of patients with advanced non-squamous non-small cell lung cancer (NSCLC), tumors harbor activating mutations in the epidermal growth factor receptor gene (EGFR), with relevant clinical and therapeutic implications that make this patient population peculiar." (PMID 40075694, 2025). "In the same year, it was designated by the FDA as a breakthrough therapy for metastatic squamous and non-squamous non-small cell lung cancer (NSCLC) with PD-L1 expression which continued to progress on or after platinum-based chemotherapy or an FDA-approved EGFR or ALK targeted agent." (PMID 39974747, 2025). "Necitumumab's indication refers to “epidermal growth factor receptor (EGFR) expressing squamous non-small cell lung cancer” with no reference to activating mutations, thus there is no reference to the need of a validated test in section 4.2 and/or 4.4." (PMID 34790681, 2021). "In non-squamous non-small-cell lung cancer, 9/15 were all EGFR, ALK, and ROS1 wild-type." (PMID 33042826, 2020). "The reports of dramatic response and improvement in performance status with the use of EGFR TKIs may influence a physician’s decision-making for patients with non-squamous non-small cell lung cancer (NSCLC) and life-threatening respiratory distress." (PMID 25050082, 2014). "In their study, samples from 240 patients with metastatic non-squamous non-small cell lung cancer (NSCLC) were examined for the presence of mutant EGFR DNA using both direct DNA sequencing as well as PNA clamped PCR to suppress amplification of wild-type EGFR DNA followed by sequencing." (PMID 32059456, 2020). "Epidermal growth factor receptor (EGFR) mutation analysis has become an important part of the initial workup of non-squamous non-small cell lung cancer (NS-NSCLC) patients as it is now recognized both as a prognostic and predictive marker for therapy with EGFR tyrosine kinase inhibitors (TKIs)." (PMID 40104451, 2025). "First-line treatment of patients with metastatic, non-squamous non-small cell lung cancer (NSqNSCLC), with no EGFR or ALK genomic tumor aberrations." (PMID 35037899, 2022). "Based on the information provided in both SmPC and EPAR, one could infer that the diagnostic test referred to in section 5.1 is considered a complimentary diagnostic rather than CDx as the indication of necitumumab is for squamous non-small cell lung cancer expressing EGFR." (PMID 34790681, 2021).
pancreatic adenocarcinoma (47 papers, 2005 to 2025). "EGFR expression has been detected in 25–90% of the pancreatic adenocarcinomas in different studies and is associated with stage, metastasis, poor differentiation and survival." (PMID 32310997, 2020). "Herein, we found that the expression of EGFR was associated with tumor differentiation and survivability of pancreatic adenocarcinoma, which was in line with previous reports." (PMID 29596435, 2018). "In pancreatic adenocarcinomas, Fibulin-3 binds EGFR (competitive to EGF) causing autophosphorylation of EGFR at Tyr-992 and Tyr-1068 and the subsequent phosphorylation of AKT at Thr-308 and ERK at Thr-202 and Tyr-204 and, thus, accelerates pancreatic adenocarcinoma growth." (PMID 23936443, 2013). "In pancreatic adenocarcinoma (PA), EGFR amplification is observed in approximately half of cases, while EGFR mutations are rare." (PMID 40364160, 2025). "Pancreatic adenocarcinoma shows the strongest upregulation of USP25 expression in tumors with a high EGFR expression, and this prompted us to evaluate cancer patient survival." (PMID 33202887, 2020). "The binding of REG3A to the epidermal growth factor receptor (EGFR) was suggested given that the two moieties colocalize upon immunostaining of SW1990 pancreatic adenocarcinoma cells and EGFR/REG3A complexes are detected by co-immunoprecipitation." (PMID 31696115, 2019). "Hung and colleagues recently demonstrated that hRNase5/ANG functions as a ligand of EGFR and a serum biomarker to predict EGFR-TKI erlotinib response in patients with pancreatic adenocarcinoma." (PMID 30449278, 2018). "In MYB-silenced cells, the pancreatic adenocarcinoma signaling was also negatively regulated due to the inhibition of EGFR and NF-κB." (PMID 27354262, 2016). "Enhanced AGR2 expression and activated EGFR signaling is present in all pancreatic adenocarcinomas, chronic pancreatitis, and premalignant pancreatic intraepithelial neoplasias." (PMID 27764193, 2016). "Mice with subcutaneous BxPC-3 pancreatic adenocarcinomas were divided into five groups receiving vehicle or mAb mixtures directed against either EGFR (HER1), HER2, HER3 or all three receptors combined by Pan-HER." (PMID 26460961, 2015). "In pancreatic adenocarcinoma, the EGFR tyrosine kinase domain is highly conserved, which indicates that this tumor is responsive to EGFR target therapy." (PMID 24722501, 2014). "Moreover, the transforming growth factor alpha (TGF-alpha) is abundant in pancreatic nerves, and the epidermal growth factor receptor (EGFR) is prominent in adenocarcinoma cells, constituting a growth advantage of pancreatic adenocarcinoma." (PMID 37297000, 2023). "Additionally, high expression of EGFR has been related to shorter survival of pancreatic adenocarcinoma." (PMID 29596435, 2018). "Finally, 8 differentially expressed genes (ERLIN1, HMGA2, FAM110B, EGFR, MCM2, BCL2L1, E2F1 and RAC1) were considered to be significantly negatively associated with survival (P < 0.05) time of pancreatic adenocarcinoma patients." (PMID 29596435, 2018). "However, the benefit of EGFR blockade in pancreatic adenocarcinomas is small for the EGFR independent activation of ErbB3/PI3K/Akt7." (PMID 27609096, 2016). "TATI/SPINK1 is expressed together with EGFR in pancreatic adenocarcinomas." (PMID 24204699, 2013). "Alternatively, NF-κB might be induced via EGFR-mediated pathways, since EGFR was found to be overexpressed in 30–50% of pancreatic adenocarcinomas, and EGFR activation was proposed to lead to NF-κB activation in cell lines." (PMID 17622249, 2007). "DCA activates EGFR, MAPK, and STAT3 signaling through TGR5 receptor and induces tumorigenicity in pancreatic adenocarcinoma cells." (PMID 37145211, 2023). "We identified seven prognostic genes (MET, DYNLL2, CDK1, TNFSF10, PIP5K1C, MSLN, GKN1) and validated that their related proteins, such as EGFR and MMP2, have a significant impact on the prognosis of pancreatic adenocarcinoma." (PMID 37370756, 2023).
pancreatic adenocarcinoma (continued). "In pancreatic adenocarcinoma, there was significant correlation between the expression of FAM83H mRNA and EGFR mRNA (Pearson correlation, R = 0.27, p < 0.001), and the expression of ZNF16 mRNA and EGFR mRNA (Pearson correlation, R = 0.33, p < 0.001)." (PMID 32460791, 2020). "Although the anti-EGFR BiTE showed a potent antitumor effect against pancreatic adenocarcinoma COLO 356/FG, it was not effective for LS174T xenograft growth compared to cetuximab." (PMID 40943224, 2025). "It is worthy to note that another EGFR-directed clinical trial testing cetuximab as adjuvant therapy with gemcitabine in patients with advanced pancreatic adenocarcinoma did not improve the overall survival compared with patients treated with gemcitabine alone." (PMID 30449278, 2018).
prostate tumor (47 papers, 2000 to 2025). "The increased activity of the EGF/EGFR complex that is associated with prostate tumour progression leads to the activation of different downstream signalling pathways including MEKK/ERK and PI3K/AKT (Phosphoinositide 3-OH Kinase)." (PMID 24796332, 2014). "Thus, loss of EGFR regulation and altered signalling may, in part, explain the transition of prostate tumours from androgen dependent to androgen independent." (PMID 19888222, 2009). "This is really important as the intercommunication between GPCR and EGFR provides another available pathway for the survival of tumour cells, including prostate tumour cells." (PMID 39456984, 2024). "Lastly, we investigated the possibility of targeting EGFR signaling in the treatment of prostate tumors." (PMID 37463954, 2023). "While prostate tumors in an androgen replete setting are predicted to be highly resistant to EGFR targeting drugs, a distinct vulnerability is developed during progression to ENZR." (PMID 36167836, 2022). "Aberrant activation of EGFR is common in prostate tumors and correlates with shorter time of prognosis to castration-resistant prostate cancer (CRPC)." (PMID 36228719, 2022). "As a result of the overexpression of TF ESF1, miRNA MIR133A1 is downregulated to upregulate the target gene EGFR, responsible for cell proliferation, local recurrence, and distant-organ metastasis in prostate tumors." (PMID 35164166, 2022). "Alternative transcripts were recurrently identified in EGFR (i.e., vIII, vIVb) within CNS tumors in AR (e.g., v7) within prostate tumors, and in MET (e.g., exon 14 skipping) within breast and lung (data not shown) tumors." (PMID 33889297, 2021). "Overall, these data suggest that high protein levels of KIF15 correlated with increased EGFR protein levels in prostate tumor samples." (PMID 34804913, 2021). "When αEGFR-CAR+ NK cells were co-cultured with EGFR+ PC-3 prostate tumor spheroids, the spheroid size significantly decreased compared to co-culture with GFP control knock-in NK cells." (PMID 34162850, 2021). "In order to further examine the clinical relevance of EGFR expression, we compared EGFR mRNA expression between normal prostate tissues adjacent to the prostate tumor tissues, primary PCa tissues, as well as PCa metastatic lesions." (PMID 30134822, 2018). "A previous study demonstrated that EGFR promoted prostate tumor-initiating cells and circulating tumor cells survival, and EGFR inhibitor led to suppression of tumor xenograft growth." (PMID 29137265, 2017). "This circuit appears to be operant in the clinical setting here reported, as in human prostate tumours mPGES-1 and EGFR are concomitantly expressed in specimens with a high Gleason score compared to specimens of organ-confined lesions with a low Gleason score." (PMID 26113609, 2015). "Seven transmembrane receptors have been shown to heterodimerize with ERBB family members and studies have demonstrated that the CXCR7 co-receptor CXCR4 interacts with EGFR in other types of cancer, like tumors of the prostate and bladder." (PMID 25168820, 2014). "Our study provides rationale for targeting Akt, EGFR, Src, Bcl-2, and AR signaling as a treatment for AR-positive relapsed prostate tumors after hormone therapy." (PMID 24349321, 2013). "It is especially noteworthy that overexpression of EGFR has been widely observed in AA prostate tumors." (PMID 21992608, 2011). "One caveat that deserves specific mention is that EGFR signalling contributes to numerous aspects of prostate tumour progression." (PMID 17406365, 2007). "Prostate tumor study that used MALDI to examine EGFR/VEGFR inhibitor AEE788 in xenografts." (PMID 41228317, 2025). "In conclusion, combination therapy between the GHRH-R antagonist and the EGFR inhibitor could act synergistically in prostate tumour cells, blocking tumour processes." (PMID 39456984, 2024).